TM4SF1 (transmembrane 4 L six family member 1)
Diseases named in the same sentence as TM4SF1 in open-access papers (continued):
Sharing a sentence is not in itself a finding about the gene and the disease.
tumor (continued). "We surveyed TM4SF1 expression in cultured endothelial cells and six non-endothelial cell and non-tumor cell types that originated from both human and mouse tissues." (PMID 39590375, 2024). "We analysed the intercellular networks about LIF/LIFR and found that interactions occurred frequently between TM4SF1+ tumor cells and proliferative tumor cells, indicating that LIF were mainly secreted from TM4SF1+ or proliferative tumor cells exerted an effect on other cell types." (PMID 37360193, 2023). "We chose TM4SF1, CD44, CD133, and OCT4 as the primary antibodies to combine with tumor tissues." (PMID 37069693, 2023). "Among them, TM4SF1, TM4SF4, and TM4SF5 are grouped under the transmembrane 4 L6 domain family, and they have been studied for their expression and roles in various tumor biological activities." (PMID 36678607, 2023). "Particularly, we found that TM4SF1 and LIF might serve as tumor progression markers in patients with CRC." (PMID 37360193, 2023). "The results showed that these paired samples exhibited a lower TM4SF1 expression in the tumor tissues (61.54%, 8/13), compared with matched noncancerous tissue samples (7.69%, 1/13)." (PMID 29665316, 2018). "Previous study indicated that transfection and over‐expression of TM4SF1 in HeLa cells had no impact on tumor cell proliferation but rather enhanced the migration ability of HeLa cells and contributed to the metastatic phenotype 16." (PMID 29123978, 2017). "Similar to TM4SF1, TM4SF5 expression resulted in the internalization of CD63 from the cell surface to the lysosomes, thus decreasing CD63 level on the membrane surface and reducing its tumor suppressive actions." (PMID 25033048, 2014). "We previously reported that in human tumor xenografts in mice, an ADC directed to mouse TM4SF1 (2A7A-LP2) effectively regressed tumors through an anti-vascular mechanism, and an ADC directed to human TM4SF1 (v1.10-LP2) effectively regressed tumors through an anti-tumor cell mechanism." (PMID 42196417, 2026). "VAR03c and VAR09c were the only HV tumor cell clusters with absent TM4SF1 expression." (PMID 40527915, 2025). "Hence, we can assume that TM4SF1 may activate the NOTCH pathway via upregulation of MYH9, ultimately promoting tumor stemness in HCC." (PMID 37069693, 2023). "Tissue microarrays (TMA) show that TM4SF1 expression is strongly higher in ESCC tissues than in non-tumor tissues, and upregulated TM4SF1 is significantly associated with TNM stage, N classification, differentiation, tumor size, and poor overall survival." (PMID 35835740, 2022). "Clinicopathologic features and survival analysis demonstrated that RNASET2 protein was significantly correlated with tumor cell differentiation, Lauren's classification, and TM4SF1 protein expression, but not correlated with lymph nodal metastasis and patient's prognosis." (PMID 32528897, 2020). "Five genes, ROBO4, SNRK, TM4SF1, FMO2 and TIMP3, found in this screen have been preferentially associated with capillary endothelial cells from mouse lung and TMBM expression was found specifically in tumour endothelial cells, but not normal endothelial cells." (PMID 16390543, 2006). "TM4SF1 expression was positively correlated with TNM stage (P = 0.016), N classification (P = 0.027), differentiation (P = 0.031) and tumor size (P = 0.023), but not with gender, age, smoking history, and T classification (P > 0.05)." (PMID 35835740, 2022). "In the current study, we found that the expression of TM4SF1 was negatively correlated with depth of invasion, nodal metastasis, TNM stage, and Lauren classification, but not correlated with age, gender, tumor size, or distant metastasis." (PMID 29665316, 2018). "Knockdown of ARHGDIA, COBLL1, and TM4SF1 resulted in increased levels of apoptosis in normal cells (ARHGDIA only) and tumor cells (ARHGDIA, COBLL1, TM4SF1) relative to negative controls." (PMID 21569526, 2011).
tumor (continued). "Furthermore, TM4SF1 silencing distinctly suppressed OC cell migration and invasion (e.g., HO8910PM and SKOV3), as well as xenograft tumor growth in nude mice, but that did not affect cell proliferation, cell growth, or cell cycle." (PMID 36678607, 2023).
adenocarcinoma (3 papers, 2007 to 2019). A common cancer characterized by the presence of malignant glandular cells. "For example, Tm4sf1 it was up-regulated in human adenocarcinoma A549 cell line, suggesting a poor prognosis for anticancer therapy." (PMID 25278030, 2014).
TM4SF1 also shares sentences with these, for which no sentence is quoted: cervical cancer (4 papers); lung squamous cell cancer (3); squamous cell carcinoma (3); connective tissue disorder (1); diabetes (1); endometrial cancer (1); epithelial ovarian tumor (1); gastric adenocarcinoma (1); gynecological benign tumor (1); mesothelioma (1); Obesity (1); oral squamous cell carcinomas (1); protein misfolding disorders (1); pulmonary fibrosis (1).